DACT3 (dishevelled binding antagonist of beta catenin 3)
Description:
May be involved in regulation of intracellular signaling pathways during development. Specifically thought to play a role in canonical and/or non-canonical Wnt signaling pathways through interaction with DSH (Dishevelled) family proteins.
Synonyms: RRR1; MGC15476; DAPPER3
Tractability: No criterion of Open Targets' tractability assessment is met for any kind of drug.
Gene: Protein-coding gene on chromosome 19 (46,647,551 to 46,661,182, reverse strand). Ensembl gene ENSG00000197380.
Subcellular location (Human Protein Atlas): Vesicles; Nucleoplasm
Gene Ontology:
Molecular function: delta-catenin binding; protein kinase A binding; protein kinase C binding; identical protein binding
Biological process: negative regulation of canonical Wnt signaling pathway; negative regulation of cell growth; negative regulation of Wnt signaling pathway
Cellular component: cytoplasm
Genetic constraint (gnomAD): Loss-of-function variants: 5 observed, 14.96 expected, observed/expected ratio (o/e) 0.33, 90% interval 0.17 to 0.7. The synonymous counts are far from expectation, so gnomAD's model fits this gene poorly and the ratio says little. Missense variants: 908 observed, 680.09 expected, observed/expected ratio (o/e) 1.34, 90% interval 1.26 to 1.41. Synonymous variants: 454 observed, 310.77 expected, observed/expected ratio (o/e) 1.46, 90% interval 1.35 to 1.58.
Homologues: Orthologues: macaque DACT3 (99% identical), pig DACT3 (95% identical), dog DACT3 (94% identical), mouse Dact3 (85% identical), rat Dact3 (84% identical), guinea pig DACT3 (66% identical), zebrafish dact3a (31% identical), chimpanzee DACT3 (27% identical). Paralogues in human: DACT1 (30% identical), DACT2 (21% identical).
Diseases named in the same sentence as DACT3 in open-access papers:
DACT3 is named in the same sentence as 14 diseases in open-access papers, as found by Europe PMC text mining. Sharing a sentence is not in itself a finding about the gene and the disease. The quoted sentences say what the papers report.
colorectal cancer (9 papers, 2011 to 2022). A primary or metastatic malignant neoplasm that affects the colon or rectum. "This bivalent histone state was associated with decreased DACT3 expression in colorectal cancer cell lines." (PMID 28148257, 2017). "It was reported that epigenetic reduction of DACT3 caused aberrant Wnt/β-catenin signaling in colorectal cancer cells and might be a potential pharmacological target for histone modification." (PMID 34368222, 2021). "In colorectal cancer, Dishevelled-binding antagonist of beta-catenin 3 (DACT3), an antagonist of Dishevelled, was found to be regulated by bivalent histone modifications—activating H3K4me3 and repressive H3K27me3 histone marks—at its locus." (PMID 28148257, 2017). "DACT3 is down-regulated in colorectal cancers by epigenetic mechanisms including histone methylation and deacetylation." (PMID 21931769, 2011). "Consistently, DACT3 interacted with and down-regulated Dvl2 protein and attenuated the Wnt-responsive Top flash reporter expression, which agrees with the inhibitory effect of DACT3 on Wnt signaling in colorectal cancer." (PMID 35864965, 2022). "In addition, it is suggested that overexpression of DACT3 resulted in a dramatic activation of caspase 3 in colorectal cancer cells and induced a sharp drop in the mitochondrial transmembrane potential that is characteristic of apoptosis." (PMID 35864965, 2022). "In a former study, DACT3 (a negative regulator of Wnt/β-catenin pathway) could inhibit Wnt/ß-catenin activity although the activating mark H3K4me3 remained at high levels near the DACT3 transcription start site in colorectal cancer cells." (PMID 32245092, 2020). "The histone modification may be the main regulated mechanism of DACT3 in colorectal cancer." (PMID 28077137, 2017). "DACT3 is underexpressed in COAD and is an epigenetic regulator of Wnt/β-catenin, this gene was proven to be a prognostic factor for colorectal cancer." (PMID 34073426, 2021).
colon cancer (5 papers, 2009 to 2022). "Further analysis showed DACT3 expression was related to prognosis and validated to be associated with the pathological stage of colon cancer." (PMID 35864965, 2022). "DACT1 was frequently downregulated by promoter methylation in HCC, whereas another DACT family member, DACT3, was repressed by bivalent histone modifications in colon cancer." (PMID 23497530, 2013). "According to the research, histone modification may be the main regulated mechanism for the inactivation of DACT3 in colon cancer." (PMID 35864965, 2022). "There is reduced DACT3 expression in human colon tumors due to histone modifications, resulting in increased Wnt signaling activity; this suppression of DACT3 expression is relieved in colon cancer cell lines by treatment with histone methylation and deacetylase inhibitors." (PMID 19440376, 2009).
lung cancer (4 papers, 2010 to 2023). A malignant neoplasm involving the lung. "MiR-31 directly inhibits the expression of Dkk-1 and DACT3 in lung cancer cells as well as normal respiratory epithelium." (PMID 38309281, 2023). "Over-expression of miR-31 significantly enhanced proliferation by direct interaction with Dickkopf-1 and DACT-3 in lung cancer." (PMID 35864965, 2022). "DACT3 was also demonstrated to inhibit the malignancy in other cancers such as non–small-cell lung cancer and esophageal squamous cell carcinoma." (PMID 34368222, 2021). "Over-expression of miR-31 markedly diminished Dkk-1 and DACT3 expression levels in normal respiratory epithelia and lung cancer cells." (PMID 21048943, 2010). "Herein, we report that CSC induces expression of miR-31 targeting several Wnt signaling antagonists including Dickkhopf-1 (Dkk-1) and DACT3 in normal human respiratory epithelia as well as lung cancer cells." (PMID 21048943, 2010). "Collectively, these experiments strongly suggested that miR-31 modulates Dkk-1 and DACT3 via post-transcriptional and translational-inhibitory mechanisms in cultured normal respiratory epithelia and lung cancer cells." (PMID 21048943, 2010).
breast carcinoma (3 papers, 2011 to 2022). "As well as in breast cancer cells, depletion of DACT3 promote cell autophagy and tumorigenesis." (PMID 35598381, 2022). "Given the importance of Wnt/β-catenin in the mammary gland tumorigenesis in triple negative, mesenchymal breast cancers, we speculate that DACT3 represents a potential therapeutic target for these carcinomas." (PMID 21931769, 2011).
esophageal squamous cell carcinoma (2 papers, 2021 to 2022). Esophageal squamous cell carcinoma (ESCC) is a type of esophageal carcinoma (EC) that can affect any part of the esophagus, but is usually located in the upper or middle third. "DACT3 was demonstrated as a tumor suppressor in several malignant cancers, such as esophageal squamous cell carcinoma and non-small cell lung cancer." (PMID 35598381, 2022).
esophageal cancer (1 paper, 2017). A primary or metastatic malignant neoplasm involving the esophagus. "In the present study, we found the expression of DACT1, DACT2 and DACT3 were frequently silenced or decreased in esophageal cancer cell lines." (PMID 28077137, 2017). "Frequent reduced expression of DACT1, DACT2 and DACT3 were found in esophageal cancer cell lines and the expression levels of DACT1 and DACT2 were reversed by 5-Aza-Dc." (PMID 28077137, 2017). "However, DACT3 mRNA was not significantly up-regulated after treatment with 5-Aza-Dc or TSA in four esophageal cancer cell lines." (PMID 28077137, 2017).
cancer (9 papers, 2011 to 2022). A tumor composed of atypical neoplastic, often pleomorphic cells that invade other tissues. "It needs to further investigate the molecular mechanism of DACT3 in cancer cell autophagy and its potential therapeutic implications." (PMID 35864965, 2022). "As a member of DACTs, the expression of DACT3 is also modulated by miRNAs in cancers." (PMID 35864965, 2022). "DACT3 is a third DACT family member and has been revealed as a negative regulator of Wnt/β-catenin signaling, which plays an important role in cancer development." (PMID 34368222, 2021). "This allowed the selection of the key EMT-correlated genes that uncover functional implications in cancer; this is the case of direct correlation of NOX4 with DACT3 and SFRP1 and inverse correlation of NOX4 and BMP5." (PMID 34073426, 2021). "Epigenetic regulation through histone modification or DNA methylation was also shown previously for other antagonists of Wnt signaling such as DACT3, sFRPs, WIF1 and DKK-1 in different cancer cells." (PMID 23658527, 2013). "As a result, the GO functions for DACT3, TNS1, and MSRB3 included actin binding, actin cytoskeleton, negative regulation of immune system process, and cell adhesion molecule binding, which were well-recognized biological processes for metastasis of cancers." (PMID 34368222, 2021).
DACT3 also shares sentences with these, for which no sentence is quoted: tumor (4 papers); asthma (1); bladder cancer (1); gastric cancer (1); hepatocellular carcinoma (1); non-small cell lung carcinoma (1); schizophrenia (1).